CIITA (class II major histocompatibility complex transactivator)
Diseases named in the same sentence as CIITA in open-access papers (continued):
Sharing a sentence is not in itself a finding about the gene and the disease.
non-small cell lung carcinoma (3 papers, 2024 to 2025). A group of at least three distinct histological types of lung cancer, including non-small cell squamous cell carcinoma, adenocarcinoma, and large cell carcinoma. "Some studies hint towards the impact of EGFR inhibition on the induction of CIITA expression in non-small cell lung cancer; however, studies are warranted that will validate these findings in CRC and to exploit them for better patient treatment." (PMID 40141198, 2025). "For instance, lncRNA-HOXC-AS2 regulates TAM polarization through the STAT1/SOCS1 and STAT1/CIITA pathways to promote the progression of non-small cell lung cancer." (PMID 38769475, 2024).
Obesity (3 papers, 2021 to 2023). Accumulation of substantial excess body fat. "Adipocytes from humans with obesity had increased expression of multiple MHCII-related genes (CIITA, HLA-DPA1, CD74, CD80) in both VAT and SAT." (PMID 36153324, 2022). "Furthermore, at T3, we observed reduced expression of key transcription factors NFKB1, FOSB, NCOR, CIITA with pregravid obesity (2-4 fold drop in leans vs. 4-6 fold drop in obese)." (PMID 34195568, 2021).
parasitic infection (3 papers, 2012 to 2022). "Interferon-inducible GTPase 1 (IIGP1) and class II, major histocompatibility complex, transactivator (CIITA) have been selected to showcase the network of genes known to be involved in inhibition of parasitic infection." (PMID 34946170, 2021). "We also observed a decrease in H3 acetylation at the promoters of CIITA, post parasite infection." (PMID 35433496, 2022). "On parasite infection, downregulation of BRG1 and STAT1α expression was observed leading to repression of CIITA." (PMID 35433496, 2022). "Taken together, these results suggest that parasite infection leads to reduced host H3 acetylation at CIITA pI and pIV with the help of HDAC1, leading to decreased CIITA transcription." (PMID 35433496, 2022). "Therefore, we conclude that parasite infection leads to reduced BRG1 expression, further downregulating CIITA and its downstream genes." (PMID 35433496, 2022). "Thus, POR is indirectly responsible for regulation of expression of CIITA along with the molecules of MHC II group such as CD74, HLADQA1, HLADMA, HLADQB1 and HLADRB5 previously identified as genes responsible for inhibition of parasite infection." (PMID 34946170, 2021).
Burkitt lymphoma (2 papers, 2016 to 2017). A rare form of malignant mature B-cell non-Hodgkin lymphoma. "Moreover, inducing the expression of the I107R mutant with Dox in Burkitt lymphoma Namalwa cells resulted in impaired cell proliferation and the repression of Pax5, CIITA, and ID3." (PMID 28842558, 2017). "In the Burkitt lymphoma cell line Raji, which expresses mostly CIITA-FIII, both forms are expressed in similar amounts (data not shown)." (PMID 26871568, 2016).
Canavan disease (2 papers, 2025). A neurodegenerative disorder; its spectrum varies between severe forms with leukodystrophy, macrocephaly and severe developmental delay, and a very rare mild/juvenile form characterized by mild developmental delay. "One study demonstrated that oligodendrocyte progenitor cells derived from a hypoimmunogenic hiPSC line, engineered via B2M and CIITA knockout alone, successfully restored myelination in a Canavan disease animal model, a condition marked by severe demyelination." (PMID 40655027, 2025). "For instance, OPCs derived from B2M/CIITA KO iPSCs were shown to express high levels of CD47, a “do-not-eat-me” signal that inhibits phagocytosis by monocytes and macrophages, potentially facilitating their integration into the demyelinating brain of the Canavan disease." (PMID 40655027, 2025).
Crohn disease (2 papers, 2019 to 2023). A gastrointestinal disorder characterized by chronic inflammation involving all layers of the intestinal wall, noncaseating granulomas affecting the intestinal wall and regional lymph nodes, and transmural fibrosis. "CIITA, MHCII, and CD74 expression was significantly increased in IEC from Crohn’s disease (CD) patients with active disease compared to controls or CD patients in remission." (PMID 37818353, 2023).
head and neck cancer (2 papers, 2014 to 2019). A primary or metastatic malignant neoplasm affecting the head and neck. "Cell culture models based on established head and neck cancer lines have also demonstrated MHC-II expression, often in response to IFNγ, or transfection with CIITA—master regulator of MHC-II transcription." (PMID 31394808, 2019). "Thus, the upregulated expression of CIITA, RFX5, and subsequent expression of all the classical MHC-II genes and related genes required for antigen loading and presentation observed in HPV+ head and neck carcinomas are likely a consequence of IFNγ exposure." (PMID 31394808, 2019).
HTLV-2 infection (2 papers, 2013 to 2023). "The antiviral function of CIITA was first investigated in the context of HTLV-2 infection, and it was demonstrated that the transactivation function of Tax-2 was inhibited by CIITA to restrict HTLV-2 replication and infection." (PMID 37242405, 2023). "As far as HTLV-2 infection, we found that cells of both the T- and B-lineage are less permissive to HTLV-2 replication in the presence of CIITA." (PMID 23986750, 2013). "Overall, our observations indicated that physiologic amounts of CIITA may inhibit viral expression in cells that are natural target of HTLV-1 and HTLV-2 infection, suggesting that in vivo the virus may replicate preferentially in cells lacking CIITA." (PMID 23986750, 2013).
lung carcinoma (2 papers, 2022 to 2025). "Consistent with our result, the loss of CIITA converts lung cancer from anti-PD-1-sensitive to anti-PD-1-resistant." (PMID 36428951, 2022).
malignant glioma (2 papers, 2023 to 2024). A grade III or grade IV glioma arising from the central nervous system. "CIITA expression has been reported to induce malignant glioma tumor rejection by immune-related mechanisms." (PMID 39594630, 2024).
nasal polyps (2 papers, 2022). "This study showed that at least two CIITA SNPs (rs12932187 and rs11074938) and 2 haplotypes (CIITA_BL1_ ht2 and CIITA_BL1_ht5) were associated with nasal polyps development in asthmatics." (PMID 36189256, 2022).
ocular melanoma (2 papers, 2015 to 2024). A melanoma that arises from the structures of the eye or ocular adnexa. "One early study shows that MHC II silencing in the ocular melanoma cell line, Mel202, is the result of epigenetic silencing of CIITA." (PMID 25690042, 2015). "Interestingly, primary uveal melanocytes and ocular melanoma cells are resistant to IFN-γ-stimulation for the expression of MHC-II and evade immune surveillance, which could be caused by so-called silencing of CIITA expression." (PMID 39349587, 2024).
osteoporosis (2 papers, 2012 to 2022). A condition of reduced bone mass, with decreased cortical thickness and a decrease in the number and size of the trabeculae of cancellous bone (but normal chemical composition), resulting in increased fracture incidence. "They found that healthy mice with myeloid-specific CIITA overexpression develop severe osteoporosis caused by enhanced osteoclast differentiation and bone resorption without any change in osteoblast function." (PMID 35760800, 2022). "In conclusion, variation in inflammatory genes CIITA, CLEC-16A and INFG appear to contribute to bone phenotypes in elderly women and suggest a role for low-grade inflammation and MHC class II expression for osteoporosis pathogenesis." (PMID 23133532, 2012).
primary immunodeficiency (2 papers, 2015 to 2019). "RFXANK (primary immunodeficiency signaling) and CIITA (class II major histocompatibility complex transactivator involved in Antigen Presentation Pathway, Primary Immunodeficiency Signaling and TREM1 Signaling) were other high scoring molecules." (PMID 26302420, 2015).
rhabdomyosarcoma (2 papers, 2014 to 2015). A rare aggressive malignant mesenchymal neoplasm arising from skeletal muscle. "The HDACi TSA restored the expression of CIITA in rhabdomyosarcoma RD cells, and co-treatement of a DNMTi and TSA restored CIITA expression in SJRH30 cells." (PMID 25815463, 2015).
septic shock (2 papers, 2013 to 2016). Shock caused by infection; frequently caused by gram negative bacteria, although some cases have been caused by other bacteria, viruses, fungi, and protozoa; characterized by fever, chills, tachycardia, tachypnea, and hypotension. "In a cohort of 93 septic shock patients alive three days after shock, mHLA-DR was measured by flow cytometry and CD74, HLA-DRA, HLA-DMA, HLA-DMB and CIITA mRNA levels were evaluated in whole blood by qRT-PCR." (PMID 24321376, 2013).
uveal melanoma (2 papers, 2010 to 2016). A melanoma derived from melanocytes of the uveal tract. "Independently, Polycomb silencing of CIITA is described in uveal melanoma." (PMID 20634887, 2010). "This could represent a possible connection between BAP1 and expression of HLA in uveal melanoma, as study in mice showed that loss of BAP1 leads to increased levels of EZH2 (and PRC2) with repressed expression of its targets, including thus CIITA, leading ultimately to less HLA class II expression." (PMID 27764126, 2016).
atherosclerosis (1 paper, 2025). A disease characterized by the build-up of fatty material and calcium deposition in the arterial wall resulting in partial or complete occlusion of the arterial lumen. "HDAC2 can reduce the interaction between CIITA and RFX5 by protein degradation and deacetylation of CIITA, thereby counteracting the activity of CIITA and promoting the development of atherosclerosis." (PMID 40710369, 2025).
Behcet disease (1 paper, 2016). A chronic, relapsing, multisystemic vasculitis characterized by mucocutaneous lesions, as well as articular, vascular, ocular and central nervous system manifestations. "This study provides evidence that the CIITA and NOD1 gene are involved in the susceptibility to Behcet’s disease." (PMID 26833430, 2016).
brain tumors (1 paper, 2023). "Together, these experiments do not plead for any significant enhancement of the immune response against brain tumors by the restoration of CIITA expression in GB in this murine model." (PMID 38201622, 2023). "Despite previous reports of the potential of CIITA gene therapy in brain tumors to induce a potent antitumor immune response, additional control experiments in the same GL261/C57Bl/6 glioma mouse model strongly mitigate the importance of this mechanism." (PMID 38201622, 2023).
brucellosis (1 paper, 2024). Brucellosis is a bacterial infection that spreads from animals to people via unpasteurized dairy products or by exposure to contaminated animal products or infected animals. "In agreement with this, the expression levels of phagocytosis‐ and antigen‐presentation‐associated genes (e.g., CIITA, RFX5, HLA‐DPA1, WASF2) were reduced in brucellosis patients." (PMID 39135683, 2024).
childhood asthma (1 paper, 2022). "Results showed that the mRNA expression levels of CD3D, CD3G, HLA-DMB, CD69, RGS1, and CIITA were significantly upregulated in childhood asthma patients compared with healthy controls, consistent with bioinformatics analysis." (PMID 36118895, 2022). "Based on qRT-PCR validation, CD3D, CD3G, HLA-DMB, CD69, RGS1, and CIITA were shown to be upregulated in childhood asthma patients." (PMID 36118895, 2022). "Results showed that the mRNA levels of CD3D, CD3G, HLA-DMB, CD69, RGS1, and CIITA were significantly upregulated in childhood asthma patients compared with the control individuals." (PMID 36118895, 2022).
chronic hepatitis B virus infection (1 paper, 2025). Chronic form of hepatitis B infection. "CIITA SNPs have previously been shown to be associated with susceptibility to several immune mediated disorders and chronic hepatitis B virus infection, whereas their association with AML has not been reported." (PMID 39975548, 2025).
Chronic myeloid leukemia (1 paper, 2021). "Chronic myeloid leukemia (CML) is another type of blood cancer presenting CIITA aberrations important for the prognosis of the condition." (PMID 33499042, 2021).
classical Hodgkin lymphoma (1 paper, 2019). "A similar study described that genomic breaks in the CIITA locus were present in 38% of the PMBCL samples and 15% of classical Hodgkin lymphoma (cHL)." (PMID 30837326, 2019).
Co-infection (1 paper, 2018). "As for CIITA, it was better expressed when the recombinant was used alone than after co-infection with the other SIV genes, independently from the type of promoter driving its expression." (PMID 29385169, 2018). "Co-infection experiments using FP recombinants expressing Gag/Pro or Env with CIITA demonstrated that CIITA can increase the levels of gag/pro and env gene products." (PMID 29385169, 2018). "However, in spite of the initial decrease, CIITA expression increased over time when co-infection was performed, and enhanced the expression of both gp and env transgenes." (PMID 29385169, 2018). "Similarly, CIITA driven by the H6 promoter is better expressed when used alone than after co-infection (Ib vs IIb and IIIb, p <0.001), but its expression significantly increases over time (IIb and IIIb, day 6 vs days 1 and 3, p <0.001)." (PMID 29385169, 2018). "The failure of CIITA in enhancing the env-specific humoral immunity after co-infection with FPenv was not so obvious and might be due to the presence of the second transgene." (PMID 29385169, 2018).
colon adenocarcinoma (1 paper, 2024). "In Colon 26 murine colon adenocarcinoma cells, IFN-γ induced transcription from the CIITA-PIV locus, but not from other CIITA promoters, whereas TSA treatment induced CIITA-PIII and not CIITA-PIV." (PMID 38915093, 2024).
colorectal tumors (1 paper, 2022). "Accordingly, we found increased CIITA expression in TCGA colorectal tumors and CCLE CRC cell lines with Fbw7 mutations." (PMID 35225231, 2022). "Fbw7 loss increased MHC Class II expression and Fbw7 mutations were correlated with increased CIITA expression in TCGA colorectal tumors and cell lines, which may have immunotherapeutic implications for Fbw7-associated cancers." (PMID 35225231, 2022).
cryopyrin-associated periodic syndrome (1 paper, 2019). Cryopyrin associated periodic syndrome (CAPS) defines a group of autoinflammatory diseases, characterized by recurrent episodes of systemic inflammatory attacks in the absence of infection or autoimmune disease. "Moreover, gain-of-function mutations in and around the central NAIP, CIITA, HET-E, and TP1 (NACHT) domain of NLRP3 cause three autosomal dominantly inherited periodic fever syndromes that together are known as cryopyrin-associated periodic syndrome (CAPS)." (PMID 31525186, 2019).
cutaneous melanoma (1 paper, 2026). A primary melanoma arising from atypical melanocytes in the skin. "The authors demonstrate that AHR transactivates CIITA, thereby up-regulating antigen-presenting HLA-II molecules in cutaneous melanoma." (PMID 41964090, 2026).
dengue (1 paper, 2023). "For instance, CIITA continues to be important by providing resistance factors to modern infectious diseases such as Ebola virus and SARS-CoV-2, and IL18R1 has been shown to confer protection against more severe clinical dengue phenotypes through IL1α downregulation." (PMID 36726304, 2023).
endometriosis (1 paper, 2017). The growth of functional endometrial tissue in anatomic sites outside the uterine body. "Results from gene-based meta-analysis identified class II major histocompatibility complex transactivator (CIITA) and poly(ADP-ribose) polymerase family member 4 (PARP4) as associated with endometriosis risk at exome-wide significance level." (PMID 28900119, 2017). "Our gene-based analyses of exome-array data identified CIITA and PARP4 as significantly associated with endometriosis susceptibility." (PMID 28900119, 2017).
follicular lymphoma (1 paper, 2021). Follicular lymphoma is a form of non-Hodgkin lymphoma characterized by a proliferation of B cells whose nodular structure of follicular architecture is preserved. "We report herein a novel fusion gene involving CIITA and CREBBP in a patient with a low-grade follicular lymphoma (FL) but with high Ki-67 proliferation index." (PMID 33777766, 2021).
graft versus host disease (1 paper, 2024). An immune system disorder that occurs after allogeneic hematopoietic stem cell transplant and is a reaction of donor immune cells against host tissues. "Though these genetic disruptions to the HLA loci, CIITA, TRAC, and PD-1 present on T cells serve to mitigate the effects of graft-versus-host disease, there remains a life-threatening risk of graft-versus-host disease." (PMID 39835140, 2024).
HTLV infections (1 paper, 2013). "In this review we provided an update on the anti-viral features that make CIITA a fundamental link between adaptive and intrinsic immunity against HTLV infections." (PMID 23986750, 2013). "It is conceivable that CIITA might exert a broader effect on HTLV infection by counteracting Tax oncogenic potential." (PMID 23986750, 2013).
Insulin resistance (1 paper, 2022). Increased resistance towards insulin, that is, diminished effectiveness of insulin in reducing blood glucose levels. "CIITA is associated with MHC class II (MHCII) expression and MHCII antigen presentation in adipocytes and is reported to trigger early adipose inflammation and insulin resistance as well as inducing changes to energy expenditure in skeletal muscle." (PMID 36138412, 2022).
insulinomas (1 paper, 2017). "The immune-insulinoma connection was supported by the appearance of CIITA among the top DSG in insulinomas." (PMID 28974674, 2017). "Furthermore, many of the CIITA transcriptional targets, the MHC class II genes, were also differentially expressed in insulinoma relative to beta cells." (PMID 28974674, 2017). "For example, exon-level analysis identified the major histocompatibility II transcriptional regulator, CIITA (Simes Test FDR = 4.2 × 10−27), which was also upregulated at the DEG level in insulinomas, as being among the top 10 most differentially spliced genes (DSGs) in insulinomas." (PMID 28974674, 2017).
mastitis (1 paper, 2023). Inflammation of breast tissue during lactation or postpartum due to an obstructed duct or infection. "Among the candidate DE genes identified by DIABLO, the class II transactivator (CIITA) had one of the highest loading scores and was significantly upregulated in mastitis animals." (PMID 37403140, 2023). "CIITA was found to be a critical regulator of the immune response of Cynoglossus semilaevis towards the infection of Vibrio harvey, suggesting its putative involvement also in the molecular inflammatory process of mastitis." (PMID 37403140, 2023).
myeloid leukaemia (1 paper, 2004). "Among 26 cell lines studied, HLA-DR expression was lost from eight T-cell and two myeloid leukaemia cell lines, and this loss was closely associated with suppression of CIITA-PIV expression." (PMID 14970863, 2004). "T-cell ALL and myeloid leukaemia cell lines showed complete suppression of both CIITA-PI and CIITA-PIII, five cell lines (Molt-4, CCRF-HSB2, CCRF-CEM, PEER and K562) expressed low or negligible levels of CIITA-PIV, and five (Jurkat, SupT1, TALL1, Molt-3, and KG1) did not express it at all." (PMID 14970863, 2004).
oral cancer (1 paper, 2024). "In conclusion, CIITA modification of tumor cells alone or in synergy with immune checkpoint blockade could soon represent a suitable alternative for the treatment of oral cancer." (PMID 39035008, 2024).
pancreatic ductal adenocarcinoma (1 paper, 2018). An infiltrating adenocarcinoma that arises from the epithelial cells of the pancreas. "In a murine model of pancreatic ductal adenocarcinoma (PDA), two different cell lines were transduced with MHC class II transactivator (CIITA) and injected into syngeneic mice." (PMID 29032503, 2018).